CIMIP5 (ciliary microtubule inner protein 5)
Synonyms: C2orf50; FLJ25143
Tractability: No criterion of Open Targets' tractability assessment is met for any kind of drug.
Gene: Protein-coding gene on chromosome 2 (11,133,009 to 11,154,576, forward strand). Ensembl gene ENSG00000150873.
Subcellular location: Cell projection, cilium
Subcellular location (Human Protein Atlas): Golgi apparatus; Cytosol
Gene Ontology:
Molecular function: protein binding
Cellular component: cilium
Genetic constraint (gnomAD): Loss-of-function variants: 16 observed, 11.77 expected, observed/expected ratio (o/e) 1.36, 90% interval 0.91 to 1.88. The upper end of that interval is the gene's LOEUF score, 1.88, which puts it in group 6 of 6, group 1 being the genes least tolerant of losing a copy. Missense variants: 206 observed, 185.8 expected, observed/expected ratio (o/e) 1.11, 90% interval 0.99 to 1.24. Synonymous variants: 79 observed, 76.34 expected, observed/expected ratio (o/e) 1.03, 90% interval 0.86 to 1.25.
Homologues: Orthologues: chimpanzee C2AH2orf50 (98% identical), macaque C13H2orf50 (94% identical), dog CIMIP5 (73% identical), rat C6h2orf50 (62% identical), guinea pig CIMIP5 (56% identical), tropical clawed frog cimip5 (46% identical), zebrafish cimip5 (39% identical). Paralogues in human: CIMIP1 (19% identical).